RNU4-84P (RNA, U4 small nuclear 84, pseudogene)
Gene: Small nuclear RNA gene on chromosome 2 (98,782,410 to 98,782,548, forward strand). Ensembl gene ENSG00000201070.
Homologues: Orthologues: chimpanzee U4 (91% identical), pig U4 (63% identical), guinea pig U4 (57% identical), dog U4 (56% identical), rat LOC120102557 (53% identical). Paralogues in human: RNU4-12P (90% identical), RNU4-13P (84% identical), RNU4-44P (83% identical), RNU4-76P (83% identical), RNU4-68P (83% identical), RNU4-75P (82% identical), RNU4-42P (81% identical), RNU4-58P (81% identical), RNU4-7P (81% identical), RNU4-23P (79% identical), RNU4-35P (79% identical), RNU4-45P (79% identical), and 80 more.